SPATA9 (spermatogenesis associated 9)
Description:
May play a role in testicular development/spermatogenesis and may be an important factor in male infertility.
Synonyms: NYD-SP16; FLJ35906
Tractability: Antibody: UniProt predicts a signal peptide or a membrane-spanning region.
Gene: Protein-coding gene on chromosome 5 (95,652,181 to 95,698,711, reverse strand). Ensembl gene ENSG00000145757.
Subcellular location: Membrane
Subcellular location (Human Protein Atlas): Mitochondria
Gene Ontology:
Cellular component: membrane
Genetic constraint (gnomAD): Loss-of-function variants: 17 observed, 18.18 expected, observed/expected ratio (o/e) 0.94, 90% interval 0.64 to 1.4. The upper end of that interval is the gene's LOEUF score, 1.4, which puts it in group 5 of 6, group 1 being the genes least tolerant of losing a copy. Missense variants: 237 observed, 253.14 expected, observed/expected ratio (o/e) 0.94, 90% interval 0.84 to 1.04. Synonymous variants: 83 observed, 90.91 expected, observed/expected ratio (o/e) 0.91, 90% interval 0.76 to 1.1.
Homologues: Orthologues: chimpanzee SPATA9 (99% identical), macaque SPATA9 (97% identical), pig SPATA9 (89% identical), dog SPATA9 (88% identical), rat Spata9 (83% identical), mouse Spata9 (78% identical), guinea pig SPATA9 (64% identical), rabbit SPATA9 (61% identical).
Diseases named in the same sentence as SPATA9 in open-access papers:
SPATA9 is named in the same sentence as 2 diseases in open-access papers, as found by Europe PMC text mining. Sharing a sentence is not in itself a finding about the gene and the disease.
SPATA9 shares sentences with these, for which no sentence is quoted: Globozoospermia (1 paper); tumor (1).